ISG20 (interferon stimulated exonuclease gene 20)
Diseases named in the same sentence as ISG20 in open-access papers (continued):
Sharing a sentence is not in itself a finding about the gene and the disease.
infection (continued). "Flow cytometric analysis revealed comparable infection rates across all three cell types, indicating that ISG20 does not significantly impair BKPyV entry." (PMID 41304224, 2025). "We also examined IFN-stimulated proteins whose induction was suppressed by infection, but not by heat-inactivated virions or upon inhibition of viral DNA replication (ISG20, OASL, ZNFX1)." (PMID 38065956, 2023). "Notably, multiple antiviral proteins were also dramatically decreased in PAMs during the PRRSV-ADE infection, including ISG15, ISG20, IFIT1 (ISG56), IFIT2 (ISG54), IFIT3 (ISG60), IFIT5 (ISG58), OAS1, Mx1, RSAD2, TRIM22, TRIM25 and TRIM34, except for TRIM52." (PMID 36680075, 2022). "With the exception of CXCL10 (IP10) and interferon-stimulated gene 20 kDa protein (ISG20), both of which are dually regulated by IFN-α/β and IFN-γ, low-level ISG induction is restricted to the first weeks of infection and subsides before peak HAV RNA abundance in the liver." (PMID 30174659, 2018). "In the absence of infection, MEFs expressing ISG20 revealed an IFN-like pattern of gene expression even though exogenous IFN was not added." (PMID 30232164, 2018). "At 24 h after infection, fluorescence microscopy performed to assess GFP expression revealed a lower percentage of GFP-positive cells and reduced fluorescence intensity, suggesting that ISG20 inhibited overall replication efficiency." (PMID 30232164, 2018). "Indeed, of the ISGs examined, only ISG20 was upregulated in MRC-5 cells transduced with MyD88-expressing lentivirus relative to the MRC-5 cells transduced with the control lentivirus, and this ISG20 expression was increased upon infection with HCMV." (PMID 40638072, 2025). "Notably, we again observed that WY14643 reduced the transcripts of Ifnb, Isg15, Isg20, and Cxcl10 without infection, though the effect was not significant for Isg20 in Ppara−/− cells." (PMID 36715509, 2023). "Interestingly, MDA-5 (for melanoma differentiation-associated gene 5), MX1 (for myxovirus resistance 1), OAS1 (for oligoadenylate synthetase 1), ISG20 (for Interferon Stimulated Exonuclease Gene 20) and RIG-1 (for reticnoic acide-inducible gene 1) were up-regulated at day 5 after infection." (PMID 33490061, 2020). "Analysis of average infection-induced changes to total proteome abundance revealed that, in contrast to IAV, both IBV and IAVΔNS1 infections triggered a classical host IFN response consisting of several ISG products, including ISG15, ISG20, MDA5, MxA, IFIT1, and IFIT3." (PMID 31391303, 2019). "Although Isg20−/− mice were not more susceptible to infection with wild-type (WT) pathogenic strains of CHIKV or VEEV, an IFIT1-sensitive mutant of VEEV was more virulent in Isg20−/− mice and replicated to higher levels in some, but not all, Isg20−/− primary cells than in the WT counterparts." (PMID 30232164, 2018). "Combined with our understanding of IFN-mediated ISG20 upregulation and ISG20-mediated upregulation of IFIT1 and other antiviral effectors in vitro, the mouse model of VEEV-G3A suggests a feed-forward mechanism by which ISG20 amplifies IFN and ISG production in response to infection." (PMID 30232164, 2018). "lnc‐ISG20 acts as a ceRNA competing with ISG20 to bind miR‐326, reducing the inhibition of ISG20 translation and negatively regulating the replication of influenza A.36There are also retroviruses known as prototype foamy virus (PFV) that cause no clinical symptoms after infection." (PMID 38270295, 2024). "However, the dynamics of ISG20 and an extensive characterization of its intracellular distribution during homeostasis or during the context of infection are cruelly lacking and this may yield important clues as to the mechanisms of inhibition of ISG20." (PMID 35174977, 2022). "HiRIEF LC-MS/MS detected alterations in the remaining proteins, i.e., ISG20, PSMB8, PSMB10, ALDOC, and SERPINB1, emphasising the method’s ability to capture alterations deriving from infection that are not picked up by other methods." (PMID 37739942, 2023).
infection (continued). "At day 1, neither ISG20 nor JUN showed significant difference between DOCK5-wt and DOCK5-ko cells during the infections but VAMP5 was already significantly down-regulated by DOCK5-ko (H1N1: p = 0.0056, 0.1-fold change; H3N2: p = 0.0020, 0.19-fold change)." (PMID 29214055, 2017). "In the present study, we observed that several ISGs with known or proposed anti-CCHFV activity, i.e., Mx1, ISG15 and ISG20 or not defined for CCHFV like IFIT1, IFIT3, IFITM3, IFI16, and OAS3 were upregulated in the acute phase CCHFV patient samples as well as in the cell-infection model." (PMID 35437144, 2022). "Therefore, we investigated expression of IL-15 and ISGs, such as APOBEC3G, ISG15, ISG20, MX1, MX2, and RSAD2, after infection with R5-tropic, non-opsonized (HIV) and complement-opsonized (HIV-C) HIV-1 strains (BaL and YU-2)." (PMID 34634939, 2021).
tumor (39 papers, 2009 to 2026). "Enrichment analysis indicated that neuroactivity, ECM remodeling, immune response, and tumor immunity are associated with upregulated ISG20." (PMID 37380984, 2023). "IFN induced by ISG20 causes upregulation of antigen presentation-related genes and chemokines, thus enhancing tumor immunogenicity and attracting T cell infiltration." (PMID 37342328, 2023). "The expression level of ISG20 is lower in tumor tissues of OC and is associated with the prognosis of OC." (PMID 34950205, 2021). "In addition, ISG20 is often associated with immune responses, accompanied by increased macrophage count and neutrophil infiltration in tumours." (PMID 33939247, 2021). "STAT5 has been shown to transcriptionally regulate the miR-17-92 cluster in normal mammary tissue, suggesting that STAT5 can act as a tumor suppressor by promoting miR-17-92 expression, which results in reduced ISG20 expression." (PMID 40507264, 2025). "IMPDH1 and ISG20 were mainly expressed in tumor cells, while the remaining genes were less specific to tumor cell origin." (PMID 36816023, 2023). "Particularly, two interferon-stimulated factors (ISG15 and ISG20) are also found contributing to tumor growth and metastasis." (PMID 37483625, 2023). "Based on results from protein-protein interaction (PPI) networks and survival analysis, ISG20 was identified as a key gene involved in host anti-tumor immune response." (PMID 37342328, 2023). "Results showed that the expression level of genes including MORF4L2, CTSL1, WIPF1, CXCL13, C5orf15, LIPA, and ISG20 significantly elevated in tumor tissues." (PMID 36639648, 2023). "Due to the indispensability of antiviral processes and anti-tumor responses of the immune system, the correlation between ISG20 expression and immune infiltration levels in pan-cancer was analyzed in the TISDB database." (PMID 36177004, 2022). "Stable overexpression of ISG20 or SEH1L by pLVX-ISG20-IRES-Neo or pLVX-SEH1L-IRES-Neo in Caov3 cells reduced tumor growth." (PMID 34229669, 2021). "Our study established a novel six‐gene (APOC1, GLTP, ISG20, SPP1, SLC24A3 and UPP1) signature that was closely associated with the immune response and the tumour immune microenvironment." (PMID 34498424, 2021). "Our study established a novel six‐gene (APOC1, GLTP, ISG20, SPP1, SLC24A3 and UPP1) signature that was closely associated with the immune response and tumour immune microenvironment." (PMID 34498424, 2021). "The relative expression of ISG20 mRNA was significantly up-regulated in tumour tissues compared to adjacent non-tumour tissues (P=0.017)." (PMID 29963243, 2018). "In addition, the PML‐NB‐associated proteins, ISG20, OAS3, OAS1, and OASL were found to be upregulated and are considered to be tumour suppressors involved in promoting DNA cleavage, nuclear condensation, and apoptosis." (PMID 36579897, 2023). "Considering the correlation between high ISG20 expression and poor prognosis, we hypothesized that ISG20 enhances tumor immune evasion." (PMID 37380984, 2023). "We also show that ISG20 has a positive influence on tumor progression and metastasis." (PMID 34078871, 2021). "We show that uncontrolled ISG20 expression drives tumor progression and metastasis." (PMID 34078871, 2021). "Furthermore, previous studies indicated that ISG20 played a vital role in tumorigenesis and progression of neoplasms." (PMID 32003757, 2020). "Although specific functions of ISG20 in tumor cells are still largely unknown, its importance for CC growth can be explained by the aetiological role of human papillomavirus in this cancer type." (PMID 31523389, 2019). "In addition, ISG20 mRNA expression is up-regulated in HCC tumour compared to adjacent non-tumour tissues." (PMID 29963243, 2018). "ISG20 mRNA expression was higher in stage-B tumour tissues compared to that in stage-A HCC tissues." (PMID 29963243, 2018). "However, the precise mechanism by which ISG20 triggers tumours and contributes to cancer development is far from being clear." (PMID 29963243, 2018).
tumor (continued). "In support of our observations, a previous study has shown that ISG20 overexpression in HCC tumours was correlated with clinical parameters, such as vascular invasion, AFP levels and tumour sizes, as well as with poorer recurrence-free survival in HCC patients." (PMID 29963243, 2018). "Hypermethylation of ISG20 in KIRC and PAAD tumor tissues was correlated with the higher expression, suggesting that methylation of ISG20 may not underlie the increase in its expression; thus, other mechanisms may be involved in regulating ISG20 overexpression." (PMID 36177004, 2022). "Hypermethylation of ISG20 in KIRC and PAAD tumor tissues was correlated with the higher expression, suggesting that methylation of ISG20 may not be the cause of overexpression." (PMID 36177004, 2022). "Hypermethylation of ISG20 in KIRC and PAAD tumor tissues was correlated with higher expression of ISG20, suggesting that methylation of ISG20 may not underlie its overexpression." (PMID 36177004, 2022). "Furthermore, we examined expression of ISG20 mRNA in tumour and adjacent non-tumour tissues." (PMID 29963243, 2018). "Collectively, these results highlight the functions of ISG20 in neuroactivity, ECM remodeling, immune response, and tumor immunity, allowing us to revisit its immunological role in subsequent analyses." (PMID 37380984, 2023). "Isolation and profiling of the metastases core revealed which of the cells enriched in metastasis lesions (compared with distal normal tissues) were concentrated in the tumor core (e.g., Treg, PMN-MDSCs, Mon Thbs1, Mac Isg20)." (PMID 37756565, 2023). "ISG20 promoter methylation was significantly lower in BLCA, READ, and THCA tumor tissues than in the matched normal tissues, while higher in BRCA, LUSC, KIRC, and PAAD." (PMID 36177004, 2022). "By analyzing the DNMIVD database, we found that ISG20 promoter methylation was significantly lower in BLCA, READ, and THCA tumor tissues compared to the matching normal tissue, while higher in BRCA, LUSC, KIRC, and PAAD." (PMID 36177004, 2022). "DNA methylation is known to affect gene expression, and we found that ISG20 promoter methylation was significantly lower in BLCA, READ, and THCA tumor tissues compared with those in the matched normal tissues, while higher in BRCA, LUSC, KIRC, and PAAD." (PMID 36177004, 2022). "Consistent with the database results, our experiments confirmed that ISG20 and SEH1L are expressed at low levels in tumor tissues and that both of these genes can inhibit the proliferation, invasion, and migration of OS cells." (PMID 34229669, 2021). "Notably, we established a novel six‐gene (APOC1, GLTP, ISG20, SPP1, SLC24A3 and UPP1) prognostic signature and discovered for the first time that this signature was associated not only with intrinsic aggressive features but also with the tumour immune microenvironment." (PMID 34498424, 2021). "Through co‐expression analyses, we verified that APOC1, ISG20 and SPP1 had notably strong correlations with tumour‐infiltrating immune cells, highlighting new directions for further research." (PMID 34498424, 2021). "In other studies, estradiol upregulated mRNA levels of ISG20/HEM45 in human UP1, MDA-L3 and MCF-7 tumor cell lines." (PMID 22558189, 2012). "For the tumor stroma, a five gene classifier consisting of probesets for PSPHL (205048_s_at), CXCL10 (204533_at), CXCL11 (211122_s_at), ISG20 (204698_at), and GMDS (204875_s_at) was identified." (PMID 19225562, 2009). "In addition, we found that with the evolution of tumor cell status, the expression levels of FLT3LG, GALNT10, IL1B, and IMPDH1 remained stable while ISG20 gradually increased." (PMID 36816023, 2023). "The expression levels of ISG20 and SEH1L were lower in tumor tissues than in normal tissues." (PMID 34229669, 2021). "Finally, the expression and function of the unreported signature genes ISG20 and SEH1L were explored using immunohistochemistry, western blotting, qRT-PCR, proliferation, migration, invasion and xenograft tumor assays." (PMID 34229669, 2021).
tumor (continued). "ISG20 mRNA expression was up-regulated in tumour tissues compared to the expression in adjacent non-tumour tissues (P=0.017)." (PMID 29963243, 2018). "Notably, three genes in the classifier for the tumor stroma, CXCL10, CXCL11, and ISG20, are known interferon γ-regulated genes." (PMID 19225562, 2009). "The results showed that the expression levels of FLT3LG, GALNT10, IL1B, IMPDH1 and ISG20 were higher in tumor cells than in normal cells, while the remaining genes could not be identified because of the low expression levels in tumor cells." (PMID 36816023, 2023). "We applied immunohistochemistry, western blotting and qRT-PCR to detect the differences in the expression of ISG20 and SEH1L between paired tumor tissues and adjacent non-tumor tissues." (PMID 34229669, 2021).
cancer (17 papers, 2011 to 2026). A tumor composed of atypical neoplastic, often pleomorphic cells that invade other tissues. "By analyzing the immune landscape of NBL, we identified six genes - BATF, CXCR3, GIMAP5, GPR8, IGHM, and ISG20-with diagnostic and clinical significance in other cancers, but whose roles in NBL remain largely unexplored." (PMID 39559348, 2024). "Accordingly, ISG20 upregulation was associated with coagulation, epithelial-mesenchymal transition, angiogenesis, complement, and cancer/immune-related signaling, such as KRAS, PI3K-AKT-mTOR, and IL6-JAK-STAT3." (PMID 37380984, 2023). "ISG20 expression is induced by interferons or double-stranded RNA and is associated with poor prognosis in several malignant tumors." (PMID 37380984, 2023). "Our study highlighted the value of targeting ISG20 as an alternative therapeutic strategy in combating cancer, SARS-CoV2, and other viral-caused diseases such as HAV, HBV, HCV, IAV, YFV, and BTV." (PMID 36177004, 2022). "In cancer, expression and functional loss of these proteins allows ISG20 expression, and that promotes the invasive phenotype." (PMID 34078871, 2021). "However, high expression of ISG20 in ACC and DLBC was associated with a shorter OS, suggesting that ISG20 may be a marker of unfavorable outcomes in these types of cancer." (PMID 36177004, 2022). "In general, the expression of ISG20 was higher in cancer samples than in normal samples (P < 0.001)." (PMID 37380984, 2023). "We further validated the expression levels of ISG20 in human cancer and normal samples using RNA-seq data derived from the TCGA and GTEx databases." (PMID 37380984, 2023). "We explored the transcriptional expression of ISG20 in human cancer and normal samples using microarray data from the GENT2 database." (PMID 37380984, 2023). "Cluster 0 expressed many interferon-induced genes, such as ISG15, IRF1, ISG20, and more, which play a major role in the development and metastatic progression of cancers." (PMID 37158921, 2023). "As an enigmatic antiviral factor, it is important to know the expression levels of ISG20 in cancer tissues compared with corresponding healthy tissues." (PMID 36177004, 2022). "Herein, we performed comprehensive and integrative profiling of ISG20 expression in healthy individuals and patients using a pan-cancer dataset using genomic, transcriptomic, and epigenomic data." (PMID 36177004, 2022). "To further explore the resulting prognostic value, we analyzed the survival correlation between ISG20 mutant groups and unaltered groups in cancer." (PMID 36177004, 2022). "Cordycepin (CD) and N6, N6-dimethyladenosine (m62A) were used to treat cancer cells for ISG20 expression." (PMID 36177004, 2022). "Then, CD, a nucleoside derivative, was applied to determine the effect on ISG20 expression in the cancer cell lines." (PMID 36177004, 2022). "We analyzed ISG20 isoform prevalence and structures in pan-cancer and found 11 isoforms that exhibited differential expression levels." (PMID 36177004, 2022). "The effects of m62A, another nucleoside derivative, on ISG20 expression in cancer cell lines were also determined." (PMID 36177004, 2022). "Except for very low or no expression of isoforms ENST00000558992.1 (ISG20−010), ENST00000558942.5 (ISG20−003), and ENST00000558236.1 (ISG20−011), the remaining eight ISG20 isoforms were detectable in all cancers." (PMID 36177004, 2022). "Unlike other receptors, such as ACE2, TMPRSS4, and CTSL, increased ISG20 expression may prevent viral invasion in these types of cancer." (PMID 36177004, 2022). "Among them, higher expression of ISG20 was associated with a long OS in CESC and SKCM, suggesting that ISG20 may be a good marker for both viral prevention and cancer progress." (PMID 36177004, 2022). "Moreover, CD and m62A increase ISG20 expression in various cancer cell lines, implying the antiviral/anti-SARS-CoV-2 therapeutic potential." (PMID 36177004, 2022).